UBE2H (ubiquitin conjugating enzyme E2 H)
Description:
Accepts ubiquitin from the E1 complex and catalyzes its covalent attachment to other proteins. E2 ubiquitin conjugating enzyme that transfers ubiquitin to MAEA, a core component of the CTLH E3 ubiquitin-protein ligase complex. In vitro catalyzes 'Lys-11'- and 'Lys-48'-linked polyubiquitination. Capable, in vitro, to ubiquitinate histone H2A.
Synonyms: UBCH; UBC8; GID3; E2-20K; UBCH2
Tractability: Small molecule: it has a high-quality binding pocket. PROTAC: UniProt records ubiquitination sites on it; ubiquitination databases record sites on it; its protein half-life has been measured.
Target class: Enzyme; Transferase
Gene: Protein-coding gene on chromosome 7 (129,830,732 to 129,952,977, reverse strand). Ensembl gene ENSG00000186591.
Subcellular location (Human Protein Atlas): Mitochondria
Pathways (Reactome):
Immune System: Antigen processing: Ubiquitination & Proteasome degradation
Metabolism of proteins: Synthesis of active ubiquitin: roles of E1 and E2 enzymes
Gene Ontology:
Molecular function: protein binding; ubiquitin conjugating enzyme activity; ubiquitin-protein transferase activity
Biological process: protein K11-linked ubiquitination; protein K48-linked ubiquitination; protein polyubiquitination; ubiquitin-dependent protein catabolic process; protein ubiquitination
Cellular component: cytosol
Genetic constraint (gnomAD): Loss-of-function variants: 2 observed, 25.81 expected, observed/expected ratio (o/e) 0.0775, 90% interval 0.031 to 0.24. The upper end of that interval is the gene's LOEUF score, 0.24, which puts it in group 1 of 6, group 1 being the genes least tolerant of losing a copy. Missense variants: 62 observed, 221.37 expected, observed/expected ratio (o/e) 0.28, 90% interval 0.23 to 0.35. Synonymous variants: 66 observed, 83.42 expected, observed/expected ratio (o/e) 0.79, 90% interval 0.65 to 0.97.
Homologues: Orthologues: chimpanzee UBE2H (100% identical), dog UBE2H (100% identical), guinea pig UBE2H (100% identical), macaque UBE2H (100% identical), mouse Ube2h (100% identical), pig UBE2H (100% identical), rat Ube2h (100% identical), zebrafish ube2h (98% identical), tropical clawed frog ube2h (92% identical), rabbit UBE2H (91% identical), Drosophila melanogaster UbcE2H (79% identical), Caenorhabditis elegans ubc-8 (64% identical). Paralogues in human: UBE2T (28% identical), UBE2B (26% identical), UBE2R2 (26% identical), UBE2A (25% identical), CDC34 (25% identical), UBE2G1 (25% identical), UBE2I (23% identical), UBE2N (23% identical), UBE2C (22% identical), UBE2S (22% identical), UBE2K (21% identical), UBE2J1 (21% identical), and 12 more.
Diseases named in the same sentence as UBE2H in open-access papers:
UBE2H is named in the same sentence as 28 diseases in open-access papers, as found by Europe PMC text mining. Sharing a sentence is not in itself a finding about the gene and the disease. The quoted sentences say what the papers report.
Alzheimer disease (3 papers, 2016 to 2021). A progressive, neurodegenerative disease characterized by loss of function and death of nerve cells in several areas of the brain leading to loss of cognitive function such as memory and language. "Circulating UBE2H mRNA is a potential diagnostic marker or therapeutic target of treatment for Alzheimer’s disease." (PMID 33924823, 2021).
lung adenocarcinoma (3 papers, 2021 to 2024). A carcinoma that arises from the lung and is characterized by the presence of malignant glandular epithelial cells. "After accessing the survival data in patients with lung adenocarcinoma through online databases, a high UBE2H expression was associated with poor survival for LUAD." (PMID 33924823, 2021). "UBE2H has been observed in 75-gene signatures associated with lymph node metastasis in lung adenocarcinoma." (PMID 33924823, 2021). "UBE2H knockdown in two lung adenocarcinoma cell lines suppressed the cell migration capacity and reversed the epithelial–mesenchymal transition (EMT) signaling pathway." (PMID 33924823, 2021). "Suppressing UBE2H in cell lines of lung adenocarcinoma inhibited metastatic capacity and reversed epithelial–mesenchymal transition signaling pathway." (PMID 33924823, 2021). "Five microRNAs, including miR-101, miR-30a, miR-30b, miR-328, and miR-497, predicted to target UBE2H might be potential prognostic biomarkers for survival in lung adenocarcinoma." (PMID 33924823, 2021). "Our observations show that UBE2H is a novel regulatory molecule of metastasis, and may be a prognostic biomarker and a therapeutic target in lung adenocarcinoma." (PMID 33924823, 2021). "High expression level of Ubiquitin-conjugating enzyme E2 H (UBE2H), was identified in the metastatic malignant pleural tumor, regulated the epithelial-mesenchymal transition (EMT) program and metastasis in lung adenocarcinoma (LUAD)." (PMID 38795139, 2024). "After RNA sequencing and bioinformatic analysis from a patient with lung adenocarcinoma (LUAD), ubiquitin conjugating enzyme E2 H (UBE2H) was identified." (PMID 33924823, 2021).
amyotrophic lateral sclerosis (2 papers, 2020 to 2023). Amyotrophic lateral sclerosis (ALS) is a neurodegenerative disease characterized by progressive muscular paralysis reflecting degeneration of motor neurons in the primary motor cortex, corticospinal tracts, brainstem and spinal cord. "UBE2H acts on the ubiquitination of histones and cytoskeletal proteins related to motor neuron degeneration pathways, and multiple variants have been reported in patients with amyotrophic lateral sclerosis (ALS)." (PMID 37208785, 2023). "Furthermore, mutations of Ube2h were found in the patients who have amyotrophic lateral sclerosis (ALS), a motor neuron disease in old ages." (PMID 32403399, 2020).
autism (2 papers, 2020 to 2023). Persistent deficits in social interaction and communication and interaction as well as a markedly restricted repertoire of activity and interest as well as repetitive patterns of behavior. "Furthermore, recent genetic studies have shown that Ube2h is associated with both brain development and human brain disorders, such as autism, suggesting that UBE2H is highly polymorphic and mutations within UBE2H can affect neurodegenerative disorders." (PMID 37208785, 2023).
lung carcinoma (2 papers, 2021 to 2023). "The findings suggest that UBE2H plays a role in tumor metastasis and can be of therapeutic application in lung cancer." (PMID 33924823, 2021). "In this study, we utilized a lung cancer patient with pleural metastasis to discover a gene of interest, UBE2H." (PMID 33924823, 2021). "The progression and invasion of lung cancer were attenuated via the knockdown of UBE2H." (PMID 33924823, 2021). "Moreover, the UBE2H expression in stage 2 was significantly higher than that in stage 1 lung cancer." (PMID 33924823, 2021). "UBE2H belongs to the ubiquitin-conjugating enzyme (UBE2) family, and there are several studies investing the role of UBE2 family in carcinogenesis, especially malignant breast cancer and lung cancer." (PMID 36936424, 2023).
malignant pleural tumor (2 papers, 2021 to 2024). "A high expression level of ubiquitin conjugating enzyme E2 H (UBE2H), a hypoxia-mediated gene, was identified in the metastatic malignant pleural tumor." (PMID 33924823, 2021).
pancreatic cancer (2 papers, 2020 to 2021). "Using multivariate Cox regression analysis, we detected eight optimal ubiquitination-related genes (RNF7, NPEPPS, NCCRP1, BRCA1, TRIM37, RNF25, CDC27, and UBE2H) and then used them to construct a risk model to predict the prognosis of pancreatic cancer patients." (PMID 33414811, 2020). "UBE2H is one of the ubiquitination-related genes used to predict the prognosis of pancreatic cancer patients." (PMID 33924823, 2021).
colorectal cancer (1 paper, 2021). A primary or metastatic malignant neoplasm that affects the colon or rectum. "UBE2H has been identified in metastasis-associated gene sets in colorectal cancer." (PMID 33924823, 2021).
developmental delay (1 paper, 2023). "In the present study, we found a novel mutant variant of the UBE2H gene through genome analysis of patients with clinical phenotypes of developmental delay and intractable convulsions." (PMID 37208785, 2023). "This is the first study to report an ubiquitin pathway gene de novo heterozygous variant in the UBE2H gene, c.449C>T (p.Thr150Met), in a pediatric patient with global developmental delay, according to Online Mendelian Inheritance in Man (OMIM)." (PMID 37208785, 2023). "A de novo heterozygous variant in the UBE2H c.449C>T (p.Thr150Met) has been identified in a pediatric patient with global developmental delay and UBE2H is essential for normal neurogenesis in the brain." (PMID 37208785, 2023).
hepatoma (1 paper, 2021). "In addition, the overexpression of UBE2H enhances proliferation in murine hepatoma cells." (PMID 33924823, 2021).
mental retardation (1 paper, 2022). "Interestingly, two of the top DMGs, potassium voltage-gated channel subfamily Q member 3 (KCNQ3) and ubiquitin conjugating enzyme E2 H (UBE2H), were genes in the SFARI database and were enriched in the gene regulatory network related to ASD and mental retardation." (PMID 35978033, 2022).
Sepsis (1 paper, 2022). Sepsis is defined as life-threatening organ dysfunction caused by a dysregulated host response to infection. "In this study, WGCNA and DiffCorr were employed to find out novel hub genes including ZNF366, ZMYND11, SVIP and UBE2H, and we proposed for the first time their causative factors during sepsis progression." (PMID 35401666, 2022).
sporadic amyotrophic lateral sclerosis (1 paper, 2021). Sporadic amyotrophic lateral sclerosis is a amyotrophic lateral sclerosis in which there is no known cause, such as no family history. "The association of UBE2H and sporadic amyotrophic lateral sclerosis has been reported." (PMID 33924823, 2021).
tumor (5 papers, 2020 to 2023). "This might imply that the upregulation of UBE2H is associated with tumor metastasis, even though it is in the early stage of metastasis." (PMID 33924823, 2021). "The UBE2H expression in other patients with LUAD in different tumor stages was evaluated in the LUAD samples of the Cancer Genome Atlas (TCGA)." (PMID 33924823, 2021). "According to the expression data (fragments per kilo base per million mapped reads (FPKM)) from the RNA sequencing, the highest expression and the lowest expression of UBE2H were observed in the malignant pleural and the primary tumor tissue, respectively." (PMID 33924823, 2021). "There are few studies on the role of NCCRP1, RNF25, and UBE2H in cancer, but the existing research results suggest that these three genes also have the potential to become new tumor biomarkers or targets for cancer." (PMID 33414811, 2020). "Of the eight genes we identified, three genes (RNF7, NPEPPS, and NCCRP1) were down-regulated and the remaining five (BRCA1, TRIM37, RNF25, CDC27, and UBE2H) were up-regulated in tumor tissue compared to normal pancreatic tissue." (PMID 33414811, 2020). "As high expression levels of UBE2H were observed in the tumor samples of LUAD, we further investigated whether the expression levels of UBE2H were associated with the survival of patients through the online database of the KM plotter." (PMID 33924823, 2021). "Compared with normal tissue, a higher expression of UBE2H was observed in the tumor tissue." (PMID 33924823, 2021). "Importantly, the observed identical MFI2, MUC12, UBE2H, and TBX2 mutations were each observed in a patient-matched tumor pair and an additional tumor sample." (PMID 32604718, 2020). "Among the eight genes, five genes (BRCA1, TRIM37, RNF25, CDC27, and UBE2H) were significantly upregulated and three genes (RNF7, NPEPPS, and NCCRP1) were significantly down regulated in the tumor tissues." (PMID 33414811, 2020).
cancer (3 papers, 2008 to 2023). A tumor composed of atypical neoplastic, often pleomorphic cells that invade other tissues. "The other five genes (TMEM33, UBE2H, ATAB2D, ZBT44 and STRN) were not reported in cancers." (PMID 37407973, 2023).
infection (2 papers, 2017 to 2023). The state of being infected such as from the introduction of a foreign agent such as serum, vaccine, antigenic substance or organism. "This does not appear to be the case for the miR-183/96/182 cluster because there remains an extended region with very few reads separating the miR-183/96/182 cluster from the UBE2H read-on transcripts at 2 and 5 h after infection when induction of the cluster occurs." (PMID 28783105, 2017). "The UBE2H gene is actively transcribed before and during HSV-1 infection but as the infection progresses there is a striking accumulation of reads mapping to the intergenic region immediately downstream of the UBE2H transcription unit." (PMID 28783105, 2017).
neurological diseases (1 paper, 2023). "Although the involvement of UBE2H in neurological diseases has been reported previously, there is still a lack of understanding of the gene’s function at the cellular and organismal levels." (PMID 37208785, 2023).
UBE2H also shares sentences with these, for which no sentence is quoted: lymph node metastasis (2 papers); brain disorder (1); breast carcinoma (1); breast tumours (1); Huntington disease (1); Lewis body disease (1); liver fibrosis (1); metastasis (1); muscular atrophy (1); Parkinson disease (1); Silver Russel syndrome (1).